NCAPH (non-SMC condensin I complex subunit H)
Diseases named in the same sentence as NCAPH in open-access papers (continued):
Sharing a sentence is not in itself a finding about the gene and the disease.
tumor (continued). "Thus, elevated NCAPH levels in luminal A tumours from patients who have received hormonal therapy or chemotherapy correlate with poor long‐term outcomes, thus serving as a prognostic marker." (PMID 38344872, 2024). "Furthermore, the xenograft and metastasis mouse models also confirmed that miR-1976 inhibited tumor growth and metastasis in vivo by targeting NCAPH." (PMID 38755247, 2024). "This was in contrast with other intrinsic tumour subtypes that responded to therapy independently of NCAPH levels, except for basal tumours, which tended to respond well to chemotherapy when NCAPH levels were high." (PMID 38344872, 2024). "The unique histopathological characteristics observed may emanate from elevated levels of NCAPH in the mammary gland, thereby exacerbating genomic instability and instigating secondary oncogenic events that target diverse tumour differentiation pathways." (PMID 38344872, 2024). "As β‐catenin is closely related to aerobic glycolysis in various tumours, we next explored whether NCAPH participated in aerobic glycolysis of ccRCC cells." (PMID 36642844, 2023). "In addition, NCAPH expression was also reported to accelerate the tumor progression via PI3K-AKT signaling." (PMID 36675239, 2023). "Generally, NCAPH was expressed differently in tumor and normal samples." (PMID 35688915, 2022). "NCAPH expression was significantly upregulated in the tumor group compared with the normal group." (PMID 34399777, 2021). "This indicates that knockdown of NCAPH reduces the tumor formation ability of HeLa cells in vivo." (PMID 33311486, 2020). "Subcutaneous xenograft models were used to explore the role of NCAPH in tumor formation in vivo." (PMID 31523845, 2019). "Tumor weight and volume were significantly decreased in NCAPH knockdown cells." (PMID 31523845, 2019). "NCAPH knockdown significantly reduced tumor growth compared with that observed in control cells." (PMID 31523845, 2019). "Studies have shown that NCAPH may act as an oncogene in different tumor types." (PMID 41210692, 2025). "Our findings suggest that NCAPH is significantly overexpressed in LGG and is strongly relevant to poor prognosis, and that NCAPH plays important roles in reshaping the tumor microenvironment, which may promote immune tolerance of LGG and thus become a potential immunotherapeutic target." (PMID 41210692, 2025). "Taken together, NCAPH may play as a pro-tumor role and serve a potential therapeutic target." (PMID 38587786, 2025). "Moreover, NCAPH induces tumor promotion in several malignancies." (PMID 31892156, 2019). "We found that NCAPH protein expression in CC tissues was higher than that in corresponding adjacent non-cancerous normal tissues; in addition, the NCAPH high expression in tumor tissues of CC patients had a significantly better survival rate than NCAPH low-expression patients." (PMID 28300828, 2017). "As for the role of NCAPH in immunity, results of ESTIMATE analysis indicated that immune and stromal scores were significantly higher in H-NCAPH group, while the tumor purity score of L-NCAPH group was relatively higher." (PMID 38587786, 2025). "Furthermore, we analyzed the association between NCAPH expression and the clinicopathological characteristics of HCC patients and found that NCAPH expression was positively related to alpha fetoprotein, tumor size, tumor number, portal vein thrombus, TNM stage, and differentiation grade." (PMID 31523845, 2019). "Additionally, we observed that NCAPH-KD combined with these inhibitors resulted in a substantial reduction in the expression of NCAPH, E2F1, and Ki67 in the xenografted tumor tissues when compared to single treatments with Eve or Flav." (PMID 39991770, 2025). "In conclusion, miR-1976 inhibits NCAPH activity in LUAD and acts as a tumor suppressor." (PMID 38755247, 2024). "NCAPH overexpression promoted tumour growth, decreased the survival time, did not affect body weight, and inhibited CD8+ cell infiltration." (PMID 36642844, 2023).
tumor (continued). "In hepatocellular carcinoma, NCAPH was highly expressed in tumor tissues compared to normal noncancerous tissues and was associated with poor prognosis." (PMID 35688915, 2022). "Among the top 100 genes that have similar expression patterns of KIFC1 in the tumors of the TCGA cohort, the KIFC1 expression was significantly and positively correlated with KIF2C, NCAPH, KIF4A, TPX2, and CDCA5 expression in all of the tumor types in the TCGA database." (PMID 35327439, 2022). "It is implied that NCAPH high expression in the cytoplasm of tumor tissues, not in the cytoplasm of adjacent normal tissues is very significant and important for prognosis." (PMID 28300828, 2017). "Interestingly, high NCAPH levels were associated with poor clinical outcome of HER2+ luminal tumours (ER positive), confirming that NCAPH did not influence the outcome of HER2‐enriched tumours defined by IHC either." (PMID 38344872, 2024). "Many of the key regulators in the canonical oncogenic (tan) module were involved in the processes leading to tumor cell proliferation and survival (TPX2, NCAPH, KIF11, NUSAP1, KIF23, MCM10) but most of them have not been associated with pediatric tumors." (PMID 31988326, 2020).
NCAPH also shares sentences with these, for which no sentence is quoted: cervical squamous cell carcinoma (2 papers); liver cancer (2); Oral Squamous Cell Carcinoma (2); adenocarcinoma (1); adrenocortical carcinoma (1); borderline serous ovarian neoplasms (1); Bovine mastitis (1); cholangiocarcinoma (1); cutaneous melanoma (1); ductal carcinomas (1); esophageal carcinoma (1); Fanconi Anaemia (1); head and neck squamous cell carcinoma (1); infection (1); leukemia (1); lymphoma (1); Malignant Fibrous Histiocytoma (1); nasopharyngeal carcinoma (1); pancreatic adenocarcinoma (1); psoriasis (1); renal cell carcinoma (1); serous adenocarcinoma (1); serous ovarian cancer (1).